PTH (parathyroid hormone)
Diseases named in the same sentence as PTH in open-access papers (continued):
Sharing a sentence is not in itself a finding about the gene and the disease.
Cirrhosis (8 papers, 2016 to 2023). A chronic disorder of the liver in which liver tissue becomes scarred and is partially replaced by regenerative nodules and fibrotic tissue resulting in loss of liver function. "This study aimed to assess PTH using Doppler ultrasound in patients with cirrhosis before and after simvastatin administration." (PMID 29707200, 2018). "Our findings, along with the results from some previous uncontrolled vitamin D intervention studies, question whether vitamin D supplementation in cirrhosis patients has a clinically relevant effect on PTH homeostasis." (PMID 27171112, 2016). "Underlying mechanisms for the missing effect on PTH remain speculative, but it has been hypothesized that in patients with cirrhosis, total 25(OH)D concentrations may not be the most accurate marker for physiologically-active vitamin D." (PMID 27171112, 2016).
congestive heart failure (8 papers, 2013 to 2025). Failure of the heart to pump a sufficient amount of blood to meet the needs of the body tissues, resulting in tissue congestion and edema. "In a clinical study involving chronic heart failure patients, there was a positive correlation between endogenous PTH levels and HR, suggesting a role for PTH in the associated increased HR." (PMID 32194439, 2020). "Indeed, serum parathormone (PTH) was elevated in patients with congestive heart failure due to ischemic or dilated cardiomyopathy and hypovitaminosis D was present." (PMID 26000280, 2015). "Despite several studies revealing vitamin deficiency in congestive heart failure patients, no clear data on improvement of outcome with vitamin D supplementation exist, despite reduction of inflammatory markers and PTH level." (PMID 26000280, 2015).
epilepsy (8 papers, 2013 to 2025). A brain disorder characterized by episodes of abnormally increased neuronal discharge resulting in transient episodes of sensory or motor neurological dysfunction, or psychic dysfunction. "The present study evaluated the impact of prolonged AED therapy on biochemical markers of bone metabolism, serum calcium, vitamin D, ALP, and PTH, and its association with HRQoL among adult epilepsy patients." (PMID 41210018, 2025). "Elevated serum PTH level was well observed in rats with epilepsy compared with the control group (F: 3.44, P≤0.001)." (PMID 35656438, 2022). "While additional mechanistic studies are needed, current evidence points to altered vitamin D and sodium metabolism, elevated PTH, and dysregulated bone turnover in epilepsy patients taking AEDs." (PMID 33424724, 2020). "In this study, we also assessed the serum level of PTH, Ca, and P. The results in line with previous studies showed that the level of vitamin D, Ca and P decreased and serum PTH increased in animals with epilepsy." (PMID 35656438, 2022). "CBZ is a widely used anti‐epileptic drug (AED), and there have been multiple reports that short‐ and long‐term CBZ treatment in children and adults with epilepsy leads to low serum 25‐hydroxyvitamin D, and high serum parathyroid hormone and alkaline phosphatase." (PMID 35701367, 2022). "In an epilepsy rat model, CBZ was associated with decreased serum vitamin D and elevated PTH, as well as decreased BMC, impaired collagen crosslinks, and decreased microhardness, indicating CBZ therapy may affect bone strength and microarchitecture." (PMID 33424724, 2020). "All risk factors were analyzed like age, sex, type of epilepsy, degree of disease control, age of disease onset, duration of disease and therapy, laboratory markers (Ca, PO4, ALP, PTH, Vit D), and DEXA scan results (BMD, T scores in lumbar spine, left femur, left radius)." (PMID 29780230, 2018). "Similarly, anticonvulsants, including lamotrigine and valproic acid, have been shown to increase parathyroid hormone levels in patients with epilepsy." (PMID 25505674, 2013). "Six studies compared the serum level of PTH and the combined SMD was 0.18 (95% CI: − 0.20 to 0.43; z = 0.94, P = 0.36), showing that valproic acid did not affect the level of serum PTH in children with epilepsy." (PMID 32122313, 2020).
goiter (8 papers, 2016 to 2025). Enlargement of the thyroid gland usually caused by lack of iodine in the diet, hyperthyroidism, or thyroid nodules. "DT was significantly associated with increased age (age >55 years), duration of goiter of five or more years, toxic MNG, presence of retrosternal extension, presence of large goiter, total thyroidectomy, compressive neck symptoms, mean serum PTH levels at 48 hours, and transient vocal cord palsy." (PMID 39996189, 2025).
Hyperinsulinemia (8 papers, 2015 to 2023). An increased concentration of insulin in the blood. "Hyperinsulinemia following an oral glucose load is accompanied by suppression of parathyroid hormone (PTH) production and bone turnover and may therefore indirectly protect against bone loss." (PMID 27014187, 2015). "This may be explained by reduced mobility, higher fall frequency, inflammatory stress, inadequate levels of leptin, adiponectin, and ghrelin, hypoestrogenism and hyperinsulinism, storage of vitamin D in adipose tissue, and elevated levels of parathyroid hormone." (PMID 36294434, 2022).
Hyperkalemia (8 papers, 2017 to 2025). An abnormally increased potassium concentration in the blood. "Immobilization may also be another important factor since, in addition to sunlight deprivation, it increases bone resorption and induces hyperkalemia that inhibits the secretion of parathyroid hormone." (PMID 35270499, 2022).
liver fibrosis (8 papers, 2016 to 2025). "In a previous study published by our group, we demonstrated that high levels of PTH were significantly associated with histological indices of hepatic fibrosis, steatosis, and NASH in patients with morbid obesity before surgery." (PMID 35265372, 2022). "Overall, eight factors (higher HOMA2-IR, P1NP, age, male sex, lower osteocalcin, corrected Ca, PTH, and 25(OH)D3) were independently associated with biopsy-proven liver fibrosis in our study population." (PMID 26989059, 2016). "Recent studies have explored their impact on metabolic pathways, parathyroid hormone secretion, asthma, and liver fibrosis, revealing their broad clinical potential." (PMID 40299638, 2025). "In this current longitudinal study, we evaluated the chronological framework between the status of liver fibrosis and elevated levels of PTH." (PMID 35265372, 2022). "For instance, liver fibrosis is associated with increased levels of TGF-β1, and various inflammatory cytokines, as well as decreased production of insulin-like growth factor, lecithin-cholesterol acyltransferase, and alterations in vitamin D and parathyroid hormone metabolism." (PMID 39503877, 2025). "Serum PTH concentration was not predictive of postsurgical liver fibrosis and steatosis at six months but could predict weight loss success rate." (PMID 35265372, 2022). "Liver fibrosis markers, inflammatory indicator α-Fetoprotein (AFP), tumor necrosis factor-alpha (TNF-α), 25-hydroxyvitamin D, and PTH were estimated using immunoassay techniques." (PMID 33884041, 2021). "Moreover, PTH levels were significantly higher in patients with pathological and imaging evidence of steatosis, NASH, and hepatic fibrosis." (PMID 35265372, 2022). "Positive correlations of PTH with steatosis (evaluated via ultrasonography), liver fibrosis (measured by elastography), FIB-4, and NFS were not significant." (PMID 35265372, 2022).
medullary thyroid carcinoma (8 papers, 2013 to 2024). "The parathyroid involvement is described later across life span when compare to the medullary thyroid carcinoma and the familial cases harboring RET pathogenic variants should follow lifelong surveillance protocols of PTH and annual calcium assays." (PMID 39585007, 2024). "Calcium and parathyroid hormone (PTH) levels were also within normal limits, which excluded a parathyroid pathology, while a normal calcitonin level excluded a medullary thyroid carcinoma." (PMID 26245479, 2015). "• Patients with suspected medullary thyroid cancer (MTC) should be investigated with calcitonin and carcino-embryonic antigen levels (CEA), 24 hour catecholamine and nor metanephrine urine estimation (or plasma free nor metanephrine estimation), serum calcium and parathyroid hormone." (PMID 27841128, 2016).
morbid obesity (8 papers, 2012 to 2025). An excess of body weight, normally defined as an individual with a body mass index greater than 35 or a body weight greater than one hundred percent of ideal body weight. "It is anticipated that levels of PTH would fall, as decreased body weight caused by dietary means lowers PTH levels in those with morbid obesity." (PMID 40557180, 2025). "From the keyword bursts, it can be seen that early research focused on the association between “dietary calcium” and “morbid obesity”, as well as the physiological processes centered around “blood pressure” and “parathyroid hormone”." (PMID 39092232, 2024). "Although bariatric surgery is a successful treatment for morbid obesity, it decreases calcium absorption, resulting in a substantial decrease in bone density and, as a result, an increase in PTH levels." (PMID 35265372, 2022). "There is scarce evidence showing that the parathyroid hormone level among individuals with morbid obesity remains elevated before and after surgery, particularly in patients who underwent one-anastomosis gastric bypass (OAGB) and Roux en-Y gastric bypass." (PMID 35265372, 2022). "This study aimed to evaluate the PTH level as a predictor of hepatic function in individuals with morbid obesity who have undergone bariatric surgery." (PMID 35265372, 2022). "The novelty of the present study is the detailed evaluation of probable predictors of WL%, including serum TSH, fT4, fT3, the calculated total deiodinase, thyroid’s incretory capacities, 25(OH)D, PTH, calcium, and phosphorus levels in patients with morbid obesity." (PMID 36401211, 2022). "The role of parathyroid hormone in morbid obesity is also unclear." (PMID 23724340, 2013). "A previous study showed that an increased level of PTH is a predictive factor for nonalcoholic steatohepatitis (NASH), especially in patients with morbid obesity who were candidates for bariatric surgery." (PMID 35265372, 2022).
thalassemia (8 papers, 2013 to 2025). An inherited blood disorder characterized by a decreased synthesis of one of the polypeptide chains that form hemoglobin. "The present study suggested that the rise in FGF23 in patients with thalassemia may be associated with either the stimulating effect of PTH and 1,25(OH)2D3 on FGF23 production, or direct induction effect of ferritin." (PMID 33198660, 2020). "Moreover, a rise in FGF23 in patients with thalassemia, might be either associated with the stimulating effect of PTH and 1,25(OH)2D3, or directly related to the stimulating effect of ferritin." (PMID 33198660, 2020). "Numerous studies have been conducted to explore Ca-PTH-Vitamin D axis in thalassemia but one important unnoticed metabolic pathway in these patients is of the P homeostasis." (PMID 39982925, 2025). "Studies investigating the relationship between PTH, serum P and Fe overload in children with thalassemia are few." (PMID 39982925, 2025). "Further research has shown that thalassemia patients have high parathyroid hormone levels with a lower level of Insulin-like growth factor (IGF)." (PMID 35959170, 2022). "However, there is a lack of sufficient data evaluating the association or interaction between high serum ferritin and levels of serum l,25(OH)2D3, FGF23 and PTH in patients with thalassemia." (PMID 33198660, 2020). "Additionally, another study on 90 patients with thalassemia showed that more than 25% of them had high-normal levels of PTH and calcium." (PMID 33198660, 2020). "It seems that high ferritin levels in thalassemia patients might have had possible stimulatory effect on PTH secretion in normal parathyroid function, resulting in high-normal serum PTH and calcium." (PMID 33198660, 2020). "This study evaluates the effects of ferritin on intact PTH, FGF23, and l,25(OH)2D3 in patients with major thalassemia." (PMID 33198660, 2020).
vitamin D (8 papers, 2013 to 2025). "However, investigations of the effects of hormonal factors and nutrition on bone health have mostly focused on calcium and vitamin D deficiencies and altered parathyroid hormone (PTH) levels." (PMID 34014999, 2021). "First, vitamin D insufficiency causes parathyroid hormone (PTH) to compensate for decreased calcium absorption, a response that leads to increased intracellular calcium, which may prevent insulin target cells from sensing the intracellular calcium fluxes necessary for insulin action." (PMID 25254046, 2014). "Meanwhile, vitamin D insufficiency can activate parathyroid to induce the release of parathyroid hormone which was considered to raise SUA level, although the mechanism was not clearly explained." (PMID 23585876, 2013).
Acidosis (7 papers, 2020 to 2025). Abnormal acid accumulation or depletion of base. "But some previous reviews explain it as the propofol's effect on PTH levels by increasing catecholamines as a result of respiratory acidosis after propofol administration." (PMID 35685611, 2022). "Acidosis also decreased plasma PTH in all groups, 96.5 ± 22.3 vs. 107.3 ± 19.1 pg/mL, 113.1 ± 17.3 vs. 185.8 ± 22.2 pg/mL and 504.9 ± 75.7 vs. 1255.4 ± 181.1 pg/mL." (PMID 35268016, 2022). "Acidosis resulted in a decrease in plasma PTH in all groups, 96.5 ± 22.3 vs. 107.3 ± 19.1 pg/mL, 113.1 ± 17.3 vs. 185.8 ±22.2 pg/mL and 504.9 ± 75.7 vs. 1255.4 ± 181.1 pg/mL, although significant differences were only observed in rats with reduced renal function." (PMID 35268016, 2022).
Alzheimer disease (7 papers, 2015 to 2025). A progressive, neurodegenerative disease characterized by loss of function and death of nerve cells in several areas of the brain leading to loss of cognitive function such as memory and language. "We conducted Mendelian randomization analyses to investigate the associations of serum parathyroid hormone (S-PTH) and serum 25-hydroxyvitamin D (S-25OHD) concentrations with Alzheimer’s disease (AD)." (PMID 30200567, 2018). "Fourth, the interplay between parathyroid hormone (PTH) and vitamin D3 is critically implicated in Alzheimer’s disease pathogenesis." (PMID 40626228, 2025). "In the 1980s, studies demonstrated the direct action of PTH on memory and learning in rats; more recent research investigated PTH’s protective effect on memory in a mouse model of Alzheimer’s Disease (AD)." (PMID 38392648, 2024). "CSF: cerebrospinal fluid; AD: Alzheimer’s disease; PTH: parathyroid hormone; SAH: subarachnoid hemorrhage; SPA: serum prolidase activity." (PMID 33604214, 2021).
bipolar disorder (7 papers, 2013 to 2025). A disorder of the brain that causes unusual shifts in mood, energy, activity levels and the ability to carry out day-to-day tasks. "In line with lithium's iPTH-independent actions on calcium metabolism, our study suggests that measuring Aac concentrations is an unsuitable tool to reliably detect increased parathyroid hormone levels in lithium-treated patients with bipolar disorder." (PMID 25505674, 2013). "Our results suggest that calcium imbalance may influence the long-term outcome of bipolar disorder and highlight the importance to routinely assess PTH, Vit D and calcium levels in these patients as a marker of clinical severity." (PMID 32630307, 2020). "In this study, we assessed calcium homeostasis imbalance in a sample of patients with bipolar disorder (BD); in particular, we explored whether serum levels of PTH, Vit D and calcium influence the clinical presentation of bipolar disorder, its symptom severity and clinical outcome." (PMID 32630307, 2020). "However, approved long-term treatment options for bipolar disorder other than lithium are either known to interact with calcium metabolism and parathyroid hormone secretion or unknown." (PMID 25505674, 2013). "This study compared the demographic characteristics and serum levels of vitamin D, calcium, phosphorus, PTH, and CRP in three groups of patients, including schizophrenia, bipolar disorder, and methamphetamine-induced psychosis, with a control group." (PMID 37803327, 2023). "Furthermore, newly diagnosed, drug-naïve participants with bipolar disorder also showed increased compensatory bone formation, with increased levels of PINP, OSTEOC, and PTH, which is consistent with our findings." (PMID 39726877, 2024). "The present study is a cross-sectional case–control study examining parathyroid hormone concentrations in patients with bipolar disorder with or without a current mood episode, treated with an average of 2.5 different drugs, with lithium being part of this treatment regimen in one of the two groups." (PMID 25505674, 2013).
bone metastasis (7 papers, 2014 to 2025). Transfer of a neoplasm from its primary site to bones. "Although our cohort was clinically not considered as with bone metastasis, the marginally higher parathyroid hormone levels recorded in our cohort shed doubt on that." (PMID 34290287, 2021). "Serum levels of bone alkaline phosphatase (ALP), parathyroid hormone (PTH), 25(OH) D, osteocalcin (OC) and C terminal telopeptide were measured and compared between patients with bone metastasis and those without." (PMID 27377907, 2016).
colon carcinoma (7 papers, 1997 to 2025). "The calcium-sensing receptor, expressed in human colon epithelial cells and colon cancer cells, plays a critical role in maintaining calcium homeostasis by regulating the secretion of PTH from the parathyroid glands." (PMID 40420632, 2025). "We suspected paraneoplastic syndrome due to colon cancer because his intact parathyroid hormone (iPTH) was low (6.01 pg/mL, reference 15–65)." (PMID 35187010, 2022). "We suspected paraneoplastic syndrome because of concomitant colon cancer and low intact parathyroid hormone (PTH)." (PMID 35187010, 2022). "Using RNA extracted from human tumour samples removed during surgery, we have analysed expression of mRNA for parathyroid hormone-related protein (PTHrP) and for the PTH/PTHrP receptor by RT-PCR in a panel of human breast and colon tumours." (PMID 9376272, 1997). "These lymphocytes were not cytotoxic to HLA-A2.1+ targets not producing PTH-rP, such as peptide-unpulsed CIR-A2 and colon carcinoma SW-1463, cell lines." (PMID 11742494, 2001).
hyperaldosteronism (7 papers, 2015 to 2023). Overproduction of aldosterone by the adrenal glands, which may lead to hypokalemia and/or hypernatremia. "It has also been hypothesized that higher PTH secretion in Bartter syndrome may be secondary to hyperaldosteronism." (PMID 35137195, 2022). "Recent evidence suggests that aldosterone might functionally interact with the parathyroid hormone, and significant increases in PTH levels have been observed in patients with hyperaldosteronism." (PMID 36294359, 2022). "A growing bulk of evidence suggests that hyperaldosteronism could increase PTH levels." (PMID 26161274, 2015).
hypercortisolism (7 papers, 2016 to 2025). "In fact, urinary calcium excretion is high in patients with hypercortisolism, and hypercalciuria might decrease the serum calcium, causing parathyroid glands to have increased PTH secretion and, subsequently, stimulating bone resorption." (PMID 34445560, 2021). "Patients with hypercortisolism showed higher PTH and phosphates alkaline levels and lower 25(OH)D and osteocalcin values, while serum calcium levels are normal if corrected by albumin concentration, typically lower than those of healthy people." (PMID 34445560, 2021). "Higher PTH concentrations in patients with hypercortisolism suggest active bone resorption and secondary hyperparathyroidism." (PMID 34445560, 2021). "The absence of PTH modifies bone structure and function; the action of cortisol, or at least of hypercortisolism, on such an altered bone may cause unpredictable scenarios." (PMID 39851484, 2025).